MTOR (mechanistic target of rapamycin kinase)
Diseases named in the same sentence as MTOR in open-access papers (continued):
Sharing a sentence is not in itself a finding about the gene and the disease.
chronic myeloid leukemia (56 papers, 2007 to 2025). "The K562 cell line used in our experiments is a chronic myeloid leukemia model system, and as in many human cancers, dysregulation of the mTOR pathway is associated with disease progression." (PMID 36642223, 2023). "Wang and coworkers found that bardoxolone methyl caused mitochondrial inactivation and ER stress-mediated apoptosis though inhibition of the PI3K/AKT/mTOR pathway in human chronic myelogenous leukemia K562 cells." (PMID 31398899, 2019). "Diosgenin also enhanced ROS-dependent autophagy and cytotoxicity in chronic myeloid leukemia cells via inhibition of mammalian target of rapamycin (mTOR) signaling pathway." (PMID 29370858, 2018). "Resveratrol induces autophagy in chronic myelogenous leukemia cells by regulating the AMPK/mTOR pathway." (PMID 25812084, 2015). "AMPK activator resveratrol has been reported to inhibit growth of imitinib-resistant chronic myeloid leukemia (CML) cells by mTOR inhibition." (PMID 24457597, 2014). "Besides, TRIM22 knockdown inhibited the activation of PI3K/Akt/mTOR pathway by decreasing the level of the phosphorylated form p‐Akt and p‐mTOR in chronic myeloid leukemia." (PMID 38468469, 2024). "Recently, our group reported that the Hsp70-Bim dimer recruits the oncogenic clients AKT, Raf-1, and eIF4E and mediates eIF2 signaling, the regulation of eIF4E and p70S6K signaling, and mTOR signaling pathway activation s to support chronic myeloid leukemia (CML) cell survival." (PMID 37237369, 2023). "Indeed, CDDO-Me induces autophagy, apoptosis and endoplasmic reticulum (ER) stress with the increased ERK1/2 activity and the suppression of AKT/mTOR signaling pathway in human chronic myeloid leukemia K562 cells." (PMID 35562960, 2022). "In addition, BCR-ABL may function as a key factor to stimulate mTOR transcription in chronic myeloid leukemia (CML) through PI3KCI-Akt-FOXO signaling." (PMID 34512368, 2021). "Moreover, diosgenin not only produces cytotoxic effect on human chronic myeloid leukemia cells (K562 and BaF3-WT) but also induces autophagy accompanied by reactive oxygen species (ROS) generation and mammalian target of rapamycin (mTOR) signalling pathway inhibition." (PMID 28116217, 2016). "In chronic myeloid leukemia (CML), the BCR-Abl fusion protein constitutively stimulates the PI3K/Akt axis, leading to continuous mTOR activation and uncontrolled myeloid proliferation." (PMID 41356921, 2025). "In BCR-ABL-expressing chronic myeloid leukemia (CML) precursors and ALL cells that are positive for the Philadelphia chromosome (Ph+), metformin, and AICAR suppressed the mTOR pathway and cell growth." (PMID 23875169, 2013). "Among these genes, MTOR, STAT3, MCL1, LAMC1, and KRAS have been reported to play roles in imatinib resistance in chronic myeloid leukemia in parallel with our findings." (PMID 38916832, 2024). "We confirmed an inverse correlation between Evi1 and PTEN mRNA expression levels in human AML and chronic myeloid leukemia (CML) samples but have not checked the status of AKT/mTOR signaling." (PMID 21795762, 2011). "For example, blockade of signaling molecules within the Ras/MEK or PI3K/mTOR pathways might augment the effects of EGFR therapeutics, similar to their effects on chronic myelogenous leukemia cells when used in conjunction with the BCR-ABL inhibitor imatinib." (PMID 17973573, 2007). "In Chronic Myeloid Leukemia (CML), BCL-ABL transformed cells exhibit overly expressed mTOR activity by which activating AMPK may provide therapeutic advantages." (PMID 25812084, 2015).
oral squamous cell carcinoma (56 papers, 2008 to 2026). "This study provides the first analysis of protein expression associated with the PI3K/AKT/mTOR pathway in canine oral squamous cell carcinoma, correlating them with clinic and pathologic parameters." (PMID 35883491, 2022). "We aimed to investigate the activated form of mTOR and its downstream S6 protein in canine oral squamous cell carcinoma (OSCC), and to evaluate potential associations between protein expression and clinic-pathologic variables and survival." (PMID 35883491, 2022). "In conclusion, chrysophanol inhibits the growth of oral squamous cell carcinoma cells by modulating mTOR/PPAR-α and by causing ROS accumulation." (PMID 35723362, 2022). "Aberrations of the Akt/mTOR/pS6 pathway have been linked to various types of human cancer, including oral squamous cell carcinoma (OSCC)." (PMID 24228033, 2013). "Akt/mTOR/pS6 signaling has been identified as one of the most commonly implicated pathways in various types of human cancer, including oral squamous cell carcinoma." (PMID 24228033, 2013). "High expression in cancer-associated fibroblast (CAF) could promote oral squamous cell carcinoma proliferation by regulating PI3K/AKT/mTOR pathways to enhance glycolysis activity in CAFs." (PMID 38022584, 2023). "AZD2014 also exerts mTOR inhibition and arrests the cell cycle to increase sensitivity of oral squamous cell carcinoma to radiotherapy." (PMID 39663596, 2024). "In the previously cited literature, Per2 was shown to be involved in the progression of oral squamous cell carcinoma through the PI3K/AKT/mTOR pathway." (PMID 35599595, 2022). "As shown in the previous reports, CircEPSTI1 interacts with miR-942-5p and promotes EMT through phosphorylation of PI3K/AKT/mTOR, thereby promoting proliferation and invasion of oral squamous cell carcinoma (OSCC) cells." (PMID 35757470, 2022). "(2020) found that circEPSTI1 sponged miR-942-5p to accelerate EMT in oral squamous cell carcinoma through phosphorylation of PI3K/Akt/mTOR signalling pathway." (PMID 35175172, 2022). "Aberrant activation of the PI3K/AKT/mTOR pathway is attributed to the pathogenesis of oral squamous cell carcinoma (OSCC)." (PMID 33833339, 2021). "PER1 promotes the progression of oral squamous cell carcinoma by inhibiting autophagy-mediated apoptosis and enhancing cell proliferation in an Akt/mTOR-pathway-dependent manner." (PMID 34220965, 2021). "In the oral squamous cell carcinoma HSC-6 and CAL33 cell lines, this was associated with the activation of the mammalian target of rapamycin (mTOR)." (PMID 33114763, 2020). "GNB2L1 (RACK1 – target of miR-196b-5p) has been reported to promote progression of oral squamous cell carcinoma via the AKT/mTOR pathway and induces OSCC cell migration; invasion and metastasis." (PMID 29728663, 2018). "The alkylphosphocholine erufosine is a known Akt-mTOR inhibitor in oral squamous cell carcinoma (OSCC)." (PMID 29463797, 2018). "The cascade catalytic reaction, based on GOx (glucose to H2O2) and MnO2 (H2O2 to OH radical) for chemodynamic therapy, was combined with the inhibition of mammalian target of rapamycin (mTOR) protein kinase (by rapamycin) to combat oral squamous cell carcinoma." (PMID 39203042, 2024). "Lin and colleagues reported that UA could treat oral squamous cell carcinoma by regulating protein kinase B/mammalian target of rapamycin/nuclear factor-kappa B (Akt/mTOR/NF-κB) signaling to induce apoptosis and autophagy in Ca922 cells." (PMID 38116552, 2023). "The PI3K/AKT/mTOR pathway has a significant role in tumorigenesis in oral squamous cell carcinoma." (PMID 36831551, 2023). "Furthermore, the PI3K/AKT/mTOR pathway is affected by Per2 in oral squamous cell carcinoma, demonstrating that Per2 is a tumor suppressor in multiple mechanistic investigations." (PMID 35599595, 2022). "The wide involvement of the AKT/mTOR pathway has been noted in oral squamous cell carcinoma (OSCC)." (PMID 32384682, 2020).
oral squamous cell carcinoma (continued). "Also, it has been shown that PG was able to induce autophagy in oral squamous cell carcinoma cells by down-regulating the protein kinase B/mammalian target of the rapamycin (Akt/mTOR) signaling pathway." (PMID 30282915, 2018). "IL-6 could also regulate VEGF-C at mRNA level through Akt/mTOR signaling pathway, which effectively decreased the lymphangiogenesis and metastasis in oral squamous cell carcinoma." (PMID 25884175, 2015). "Interestingly, a study has shown that ITGB2 could activate the PI3K/AKT/mTOR axis to promote proliferation in oral squamous cell carcinoma by nicotinamide adenine diphosphate hydride oxidation." (PMID 34108992, 2021). "PER2 inhibits the proliferation of oral squamous cell carcinoma and promotes the apoptosis of OSCC cells, which is dependent on the PI3K/AKT/mTOR signaling pathway." (PMID 37069338, 2023). "The activation of mTOR also increases Slug expression and the induction of EMT in oral squamous cell carcinoma, as demonstrated by experiments conducted on the HSC-6 and CAL33 cell lines." (PMID 33114763, 2020). "The circEPSTI1/mir-942-5p/LTBP2 regulatory axis was also identified to affect the proliferation and invasion of oral squamous cell carcinoma (OSCC) cells through the acceleration of epithelial-mesenchymal transition (EMT) and phosphorylation of PI3K/Akt/mTOR signaling pathway." (PMID 35255963, 2022).
autism spectrum disorder (53 papers, 2012 to 2026). A spectrum of developmental disorders that includes autism, and Asperger syndrome. "The phosphatase and tensin homolog deleted on chromosome 10 (PTEN) is a negative regulator of the mTOR pathway and is strongly associated with autism spectrum disorder (ASD), with up to 25% of ASD patients with macrocephaly harboring PTEN mutations." (PMID 40642101, 2025). "Patients with loss-of-function mutations in the PTEN gene, a negative regulator of mTOR signaling, are predisposed to developing macrocephaly, autism spectrum disorder (ASD), seizures, and intellectual disability." (PMID 40358185, 2025). "The activity of the mTOR pathway was assessed in our study because it is critical in neurodevelopment and its dysregulation has been associated with brain disorders such as autism spectrum disorder and learning disability." (PMID 37255938, 2023). "It was reported that TRIM32 reduced PI3K‐Akt‐FoxO signalling by promoting plakoglobin‐PI3K dissociation in muscle atrophy, and TRIM32 deficiency was found to cause hypoactive mTOR in autism spectrum disorder mice model." (PMID 34921503, 2022). "TSC2 is one of the key regulators of the MTOR pathway, and is implicated in autism spectrum disorder." (PMID 36239373, 2022). "Reduced PTEN and subsequent dysregulation of the AKT/mTOR pathway have also been linked with neurodegenerative diseases, such as Alzheimer’s as well as syndromic autism spectrum disorder." (PMID 35884935, 2022). "Dysregulated mammalian target of rapamycin (mTOR) activity is associated with various neurodevelopmental disorders ranging from idiopathic autism spectrum disorders (ASD) to syndromes caused by single gene defects." (PMID 34204880, 2021). "Tuberous sclerosis complex related genes such as Tsc1 and Tsc2, which are upstream modulators of mTOR, are also associated with autism spectrum disorder and epilepsy." (PMID 32424120, 2020). "This was initially based on the discovery of several monogenic autism spectrum disorders with mutations or defects in PI3K/mTOR signaling components." (PMID 26770665, 2016). "Importantly, mTOR hyperactivity seems to be linked with the pathobiology of autism spectrum disorders (ASD)." (PMID 37108467, 2023). "Dysregulation of the mTOR pathway is associated with psychiatric disorders including autism spectrum disorders (ASD) and mood disorders (MD), in which patients often exhibit disrupted daily physiological rhythms and abnormal circadian gene expression in the brain." (PMID 36045116, 2022). "In addition, mutations in PTEN, an upstream modulator of mTOR, have been associated with autism spectrum disorder and macrocephaly." (PMID 32424120, 2020). "Dysregulation of mTOR signaling has been implicated in autism spectrum disorders." (PMID 27845329, 2016). "Taken together these data suggest that disinhibited mTOR may cause, or at least contribute to, many cases of autism spectrum disorder." (PMID 24379984, 2013). "Defects in the mTOR pathway are frequently associated with brain malformations and tumours, including epilepsy, mental retardation, intellectual disability/cognitive deficits, anxiety, attention-deficit hyperactivity disorder, and sleep disorders, as well as autism spectrum disorders (ASD)." (PMID 37108467, 2023). "Therefore, we suggest that the mTOR-dependent upregulation of p-synapsin may underlie the E/I imbalance observed in autism spectrum disorders (ASD)." (PMID 34576223, 2021). "Thus far, most reports indicate that mTOR pathway dysregulation, which regulates neurodevelopment or synaptic plasticity, is linked to impaired autophagy, leading to mTOR-associated brain diseases, including autism spectrum disorders (ASD)." (PMID 34183057, 2021). "The inhibition of GSK-3β via targeting the IL-6-mediated PI3/AKT/mTOR pathway decreases neural apoptosis and affects autism spectrum disorder via GRPR." (PMID 40843259, 2025).
autism spectrum disorder (continued). "Persistent impairments in social interaction and communication subsequently led to a formal diagnosis of autism spectrum disorder (ASD), a neurodevelopmental condition frequently linked to TSC due to the dysregulation of the mTOR signaling pathway." (PMID 39727664, 2024). "In this review, we summarize the involvement of the PI3K/Akt/mTOR pathway as well as the genetic alterations of the pathway components and its critical impact on the development of the autism spectrum disorder." (PMID 36838876, 2023). "Mutations affecting mTOR or RAS signaling underlie defined syndromes (the so-called mTORopathies and RASopathies) with high risk for Autism Spectrum Disorder (ASD)." (PMID 34828352, 2021). "Tuberous sclerosis complex (TSC), a multi-system genetic disorder often associated with autism spectrum disorder (ASD), is caused by mutations of TSC1 or TSC2, which lead to constitutive overactivation of mammalian target of rapamycin (mTOR)." (PMID 33863288, 2021). "AIMTOR further reveals mTOR-signaling dysfunctions in neurons from mouse models of autism spectrum disorder." (PMID 32620110, 2020). "The mTOR inhibitor Everolimus has been tested in Phase 1 clinical trials for targeting glutamatergic signaling for Autism Spectrum Disorders (ASDs) and Temsirolimus have similarly been reported to be used in rodents for altering mTORpathway90–92." (PMID 31270411, 2019). "Multiple lines of evidence indicate that the PI3K-Akt-mTOR pathway is overactivated in autism spectrum disorders." (PMID 31548888, 2019). "To date, few neurodevelopmental disorders have been linked to an aberrantly reduced mTOR signaling as seen in the herein described TBCK-DD, including Rett syndrome, Phelan-McDermid syndrome with autism spectrum disorder and Galloway-Mowat syndrome." (PMID 30591081, 2018). "While a role for mTOR in autism spectrum disorders is suggested, to our knowledge, our study is the first to implicate mTOR–P70S6K–nucleolin–rRNA synthesis in human RTT cerebellum." (PMID 30619462, 2018). "Numerous lines of evidence implicate dysregulated mTOR signalling in the pathogenesis of autism spectrum disorder (ASD) and related neurodevelopmental disorders." (PMID 27845329, 2016). "More recently, genome-wide association studies and analyses of chromosome copy number variations (CNVs) have revealed even more evidence for dysregulation of the PI3K/mTOR signaling complex in autism spectrum disorders." (PMID 26770665, 2016). "Thus, the potential efficacy of mTOR inhibitors warrants further investigation not only into autism spectrum disorders, but also into other neuropsychiatric and neurodegenerative diseases." (PMID 39852149, 2025). "Post-mortem investigations in individuals with autism spectrum disorder (ASD) have revealed an augmented density of excitatory synapses in their brains which could be attributed to aberrant mTOR-dependent synaptic pruning." (PMID 36838876, 2023). "Finally, dampening mTOR activity has been postulated as a potential therapeutic approach for autism spectrum disorders." (PMID 35113852, 2022). "Thus, the potential efficacy of mTOR inhibitors warrants further investigation not only for autism spectrum disorders but also for other neuropsychiatric and neurodegenerative diseases." (PMID 28775826, 2017). "Together, these findings suggest that there is a considerable subgroup of autism spectrum disorders of unknown etiology with defects in PI3K/mTOR signaling, which could qualify for a therapeutic strategy targeted at this pathway." (PMID 26770665, 2016). "Apart from this conceptual advance, our results also corroborate previous studies suggesting that dysregulated PI3K/mTOR signaling is a common pathological mechanism shared by a sub-cohort of autism spectrum disorders with unknown etiology." (PMID 26770665, 2016).
autism spectrum disorder (continued). "(ii) We depicted in real time the kinetics of depolarization-induced mTOR activation in living neurons from wild type mice and mTOR-signaling dysfunctions in neurons from Fmr1 KO mice and Shank3Δ11 mice, two mouse models of intellectual disability (ID) and autism spectrum disorder (ASD)." (PMID 32620110, 2020). "Neurodevelopmental and neurophysiological mechanisms whereby upregulated PI3K-Akt-mTOR may mediate autism spectrum disorders include excessive brain growth and neuron numbers, increased protein translation at synapses, and high E/I ratios in key neural systems." (PMID 31548888, 2019). "Mutations in the genes in the PI3K-Akt-mTOR signaling pathway, comprising PIK3CA, PTEN, mTOR, and PPP2R5D have been reported in patients with autism spectrum disorder/development delay and macrocephaly." (PMID 36838876, 2023). "Postmortem studies have revealed increased density of excitatory synapses in the brains of individuals with autism spectrum disorder (ASD), with a putative link to aberrant mTOR-dependent synaptic pruning." (PMID 34667149, 2021). "In this study, we investigated mTOR and MAPK signalling pathways in the peripheral tissue of autism spectrum disorder patients in order to identify a molecular signature both for the disease and for ASD severity." (PMID 30705255, 2019). "IL-6 activates other signaling pathways, such as the PI3K/AKT/the mammalian target of rapamycin (mTOR) glycogen synthase kinase-3 beta (GSK-3β) and gastrin-releasing peptide (GRP) receptor (GRPR) pathways, in hippocampal neurons of mice with autism spectrum disorder." (PMID 40843259, 2025). "Kit is a receptor tyrosine kinase that can activate multiple downstream effectors, including Src family kinases, PLC, PI3K/mTOR, and the MAPK pathway, the latter two notable here for their shared affiliation with synapse phenotypes and autism spectrum disorder." (PMID 38536959, 2024). "This therapeutic intervention aimed to address the dual concerns of preventing the recurrence of SEGAs and potentially mitigating autism spectrum disorder (ASD)-related symptoms, given the established role of mTOR inhibition in modulating both tumorigenic and neurodevelopmental processes." (PMID 39727664, 2024).